PISRT1 (PISRT1 lncRNA)
Synonyms: NCRNA00195
Gene: Long non-coding RNA gene on chromosome 3 (139,232,992 to 139,233,522, forward strand). Ensembl gene ENSG00000281473.
Homologues: Orthologues: mouse Gm55625 (17% identical).